CCR7 (C-C motif chemokine receptor 7)
Diseases named in the same sentence as CCR7 in open-access papers (continued):
Sharing a sentence is not in itself a finding about the gene and the disease.
psoriasis (22 papers, 2012 to 2026). An autoimmune condition characterized by red, well-delineated plaques with silvery scales that are usually on the extensor surfaces and scalp. "Chemokines encoded by CCR7, CCL2, CCL19, CXCL8, CXCL1, and CXCL2 genes have been identified as potential biomarkers of psoriasis." (PMID 40906403, 2025). "Rittié and Elder have identified CCL19 and CCR7 as potential mediators of immune organization in psoriasis." (PMID 38829444, 2024). "DCs and T cells utilize the CCR7/CCL19 axis as a conduit in influencing the pathogenesis of psoriasis via interactions within psoriatic dermal aggregates." (PMID 38596682, 2024). "Previous research has demonstrated that CCL19 and its receptor CCR7, which are expressed by central memory/naive T cells and maturing DCs, exhibit elevated expression in the dermal aggregates of psoriasis lesions." (PMID 38829444, 2024). "In healthy human skin, a skin-tropic population of TCM cells expressing skin-homing receptors CCR7 and L-selectin has been observed, with overexpression in psoriasis and depletion by alemtuzumab therapy." (PMID 39315268, 2024). "This is consistent with previous studies which identified increased CCL19 and CCR7 expression in dermal aggregates in psoriasis skin lesions." (PMID 37131254, 2023). "In this review, we discuss the role of dendritic cells (DCs) and the central chemokine receptor CCR7 in the initiation and sustainment of selected chronic inflammatory diseases: multiple sclerosis (MS), rheumatoid arthritis (RA), and psoriasis." (PMID 34361107, 2021). "This situation highlights the crucial role of CCL19 and CCR7 in the progression of psoriasis." (PMID 38829444, 2024). "In addition, the SFRP2+ inflammatory fibroblasts in psoriasis share with the COL6A5+COL18A1+ fibroblasts in atopic dermatitis the expression of CCL19 which is capable of recruiting CCR7+LAMP3+ cDC2A61." (PMID 37308489, 2023). "Another 2025 study comparing erythrodermic CTCL to chronic idiopathic erythroderma, atopic dermatitis, psoriasis, and healthy controls found that erythrodermic CTCL had expanded CD4+ malignant cells with a CCR7+SELL+ central memory phenotype." (PMID 40941016, 2025). "Our study highlighted CCR7, CCL2, CCL19, CXCL8, CXCL1, and CXCL2 as potential inflammatory biomarkers in psoriasis, illuminating their molecular mechanisms." (PMID 38829444, 2024). "In conclusion, our study highlights six chemokine genes (CCR7, CCL2, CCL19, CXCL8, CXCL1, and CXCL2) as potential biomarkers in psoriasis, providing insights into the immune and inflammatory responses as pivotal instances in disease pathogenesis." (PMID 38829444, 2024). "The study highlights six chemokine genes (CCR7, CCL2, CCL19, CXCL8, CXCL1, and CXCL2) as potential biomarkers in psoriasis, which are significantly involved in immune and inflammatory responses." (PMID 38829444, 2024). "This scenario underscores the very important role of CCR7 and CCL19 in the disease progression of psoriasis." (PMID 34361107, 2021). "CCR4-expressing CCR7+ TEM have been reported in inflamed peripheral tissues (for example, in psoriasis and juvenile idiopathic arthritis)." (PMID 22490506, 2012). "For instance, in systemic sclerosis and psoriasis, dysregulated genes like CCL2 and CCR7 contribute to fibroblast activation and the infiltration of CD4+ T and NK cells through IL-17 signaling pathway, PPAR signaling pathway, leading to skin involvement and arthritis." (PMID 40534874, 2025). "In addition, iSALT participates in the pathology of psoriasis, where CCR7 and CCL19 play important roles in the sustainment of these structures (see the section on psoriasis)." (PMID 34361107, 2021). "In contrast, in models of psoriasis, no role for CD197 (CCR7)+ monocytes/monocyte-derived dendritic cells was found in the disease process." (PMID 34681660, 2021).
rheumatoid arthritis (22 papers, 2005 to 2026). A chronic, systemic autoimmune disorder characterized by inflammation in the synovial membranes and articular surfaces. "An impaired CCR7 expression and DC migration has also been linked to amelioration of rheumatoid arthritis and humanized mice treated with an anti-human CCR7 were completely resistant to collagen-induced arthritis." (PMID 39186814, 2024). "The upregulation of CCL19 and CCL21 and their receptor CCR7 was associated to Rheumatoid arthritis pathogenesis, playing an important role in bone destruction by increasing osteoclast migration and resorption activity." (PMID 31888477, 2019). "Regarding DCs, in line with previous research showing increased expression of the chemokine receptor CCR7 in rheumatoid arthritis, JIA-associated uveitis patients also showed an elevated frequency of CCR7-positive myeloid DCs, which may contribute to their recruitment to tissues affected." (PMID 34438537, 2021). "iDC processed by a PKC inhibitor possessed augmented expression of CCR7 and migration rate to lymph nodes, which will activate functional Tregs greatly and show satisfactory tolerance-inducing effect for rheumatoid arthritis and primary Sjögren’s syndrome." (PMID 35281921, 2022). "Preventive or therapeutic treatment of humanized CCR7 mice with anti-human CCR7 mAb 8H3-16A12 can restrain or relieve the rheumatoid arthritis mouse model effectually due to the weakened migration of DCs." (PMID 35281921, 2022). "In a mouse model for rheumatoid arthritis, CCR7+ CD4+ T cells accumulated and homed to lymphoid organs where they survived and maintained autoreactivity." (PMID 35544042, 2022). "CCR7 and its specific ligands are important in rheumatoid arthritis (RA), which is an autoimmune disorder." (PMID 34770763, 2021). "Notably, a study in rheumatoid arthritis shows that CCL21/CCR7 signaling increases the number of macrophages in synovial tissue and promotes joint inflammation, making CCL21 an attractive target for therapy." (PMID 36211384, 2022). "Others have reported that CD197 (CCR7) mRNA levels in monocytes correlate to the clinical inflammation status (DAS28) in rheumatoid arthritis patients and that signaling of CD197 (CCR7) (by CCL21) promotes Th17-mediated bone loss an important destructive process in PsA." (PMID 34681660, 2021). "However, CCR7-mediated cell migration also contributes to inflammatory diseases, such as rheumatoid arthritis, or facilitates metastasis of cancer cells." (PMID 31137829, 2019). "However, CCR7 also guides T cells to inflamed synovium and thereby contributes to rheumatoid arthritis and promotes cancer cell migration and metastasis formation." (PMID 31137829, 2019). "The ligands CCL19 and CCL21, and their receptor CCR7 have been found to be involved in homing of lymphocytes to the target organ and to be localized in the lymphocytic infiltrates of the synovium in patients with rheumatoid arthritis." (PMID 17900348, 2007). "In addition, the presence of lymphoid aggregates has been described in the lungs of mice challenged with bleomycin, of mice genetically modified (CCR7−/− mice) showing an impaired homing of Treg cells, and of mice with rheumatoid arthritis‐related interstitial lung disease." (PMID 32452646, 2020). "Furthermore, our research explored the potential connection between rheumatoid arthritis (RA) and ulcerative colitis (UC) at the miRNA and gene levels, particularly focusing on the two key genes CCR7 and CXCR4." (PMID 41481752, 2026). "Lee and collaborators (2017) have shown that treatment with IL-1β and TNF-α raised CCR7 expression in both precursors and differentiated osteoclasts, increasing their migratory activity toward CCL19 and CCL21 chemokines upregulated in rheumatoid arthritis." (PMID 36831188, 2023).
rheumatoid arthritis (continued). "In psoriasis or rheumatoid arthritis, respectively, anti-TNF or FTY720 therapy downregulated CCR7 on DCs and then reduced DC aggregation in the lesional skin or dLNs, although the precise mechanism was still obfuscated." (PMID 35281921, 2022).
pancreatic cancer (20 papers, 2010 to 2024). "CCR7 expression is highly expressed in patients with pancreatic cancer and is suggested to be positively associated with poor outcomes such as short survival, lymph node metastasis, lymphangiogenesis, and angiogenesis." (PMID 34948416, 2021). "In this study, we transduced CCR7-positive PANC-1 cells with lentiviral vector expressing human CCL21 (hCCL21) to determine if CCL21 affects expression of certain genes associated with pancreatic cancer formation and development." (PMID 29687228, 2020). "Markedly upregulated expression of CCR7 was observed in patients suffered with pancreatic cancer, contributing to the enhancement of angiogenesis via chemotactically binding with CCL21." (PMID 38361743, 2024). "For instance, by influencing the EMT pathway, CCL21/CCR7 facilitated the spread of pancreatic cancer cells." (PMID 36829431, 2023). "CCR7 expression is significantly increased in patients with pancreatic cancer and induces intra-tumor angiogenesis and lymphangiogenesis through chemotactic interactions with its ligand, CCL21." (PMID 36312035, 2022). "PT45P1 cell line, derived from a grade III pancreatic cancer transfected with CCR7 and orthotopically transplanted into nude mice, gave rise to significantly larger tumors and a higher frequency of lymph vessel invasion than mock transfected cells." (PMID 35203305, 2022). "CCR7 levels were significantly increased in CD133+ pancreatic cancer stem-like cells compared to CD133− cancer cells and normal tissue and lymph nodes." (PMID 35203305, 2022). "In pancreatic tumors, however, the results were more consistent, demonstrating a role for CCR7 in lymph node metastasis, EMT and progressive pain." (PMID 35203305, 2022). "In pancreatic cancer, CCR7 expression was significantly increased in MICs as well as resected primary tumors and metastatic lymph nodes, and CCL21/CCR7 signaling promoted metastasis, EMT, and survival by modulating the ERK1/2/NF-κB pathway." (PMID 36118530, 2022). "As previously discussed for several cancers, CCR7 is associated with EMT, and this is further consolidated in pancreatic cancer." (PMID 35203305, 2022). "The Lenti-hCCL21 was transduced into PANC-1 cells, a chemokine (C-C motif) receptor 7 (CCR7)-positive human pancreatic cancer cell line." (PMID 29687228, 2020). "We therefore detected the presence of CCR7 in resected pancreatic cancer tissues, metastatic lymph nodes, normal lymph nodes, adjacent normal tissues." (PMID 27505247, 2016). "CCR7 expression was up-regulated in resected pancreatic cancer tissues and metastatic lymph nodes, especially, in metastatic lymph nodes (15 folds) compared with adjacent normal tissues and normal lymph nodes." (PMID 27505247, 2016). "CCR7 protein levels were detected in normal lymph nodes, adjacent normal tissues, resected pancreatic cancer tissues, and metastatic lymph nodes by immunohistochemistry." (PMID 27505247, 2016). "CCR7 protein levels were increased in resected pancreatic cancer tissues and metastatic lymph nodes compared with adjacent normal tissues and normal lymph node." (PMID 27505247, 2016). "The results of the present study detected high levels of CCL21/CCR7 in pancreatic carcinoma tissues and metastasis lymph nodes." (PMID 27505247, 2016). "Of the same family, CCR7 combined with its ligand CCL21 was recently reported to synergistically guide pancreatic cancer cells toward lymphatic vessels and promote lymph node metastasis." (PMID 24587996, 2014). "We measured CCR2, CCR5, CCR6, and CCR7, on DCs before and after surgical removal of the pancreatic tumor mass." (PMID 20976171, 2010). "Furthermore, CCR7 expression is correlated with poor prognosis in gastric cancer, esophageal squamous cell carcinoma, pancreatic cancer, urinary bladder cancer, and renal cell carcinoma." (PMID 36980764, 2023). "CCL21 levels were low and CCR7 levels high in pancreatic cancer tissue compared to normal pancreas." (PMID 35203305, 2022).
pancreatic cancer (continued). "In contrast, the CCL21/CCR7 axis signal also plays an important role in pancreatic cancer." (PMID 34948416, 2021). "To determine if pancreatic cancer stem-like cells were a suitable model for CCR7-mediated potentiality of CCL21-driven pancreatic carcinoma metastasis, we evaluated chemokine receptor expression levels in total, CD133+, and CD133− pancreatic cancer cells by RT-qPCR." (PMID 27505247, 2016). "We tested the hypothesis that CCL21/CCR7 increases the migration potentiality of pancreatic cancer stem-like cells as well as promoting survival, by CCR7 knockdown with small interfering (si) RNA." (PMID 27505247, 2016). "We examined the ability of CCL21/CCR7 to promote CD133+ pancreatic cancer stem-like cells survival." (PMID 27505247, 2016). "CCR7 expression levels were analyzed by immunohistochemical staining and RT-qPCR in resected tumor tissues, metastatic lymph nodes, normal lymph nodes and adjacent normal tissues from patients with pancreatic carcinoma." (PMID 27505247, 2016). "Besides, we have introduced two biologically relevant triplets, namely Klk1 and {Gh1, Cst3} and Lamc2 and {Dhps, Ccr7}, which may be specifically involved in the onset of pancreatic cancer." (PMID 35180880, 2022). "Unfortunately, CCL19 expression was not evaluated in this study; however, the available data suggests that CCR7, presumably activated by CCL19, allows for pancreatic cancer metastasis to lymphoid tissue." (PMID 35203305, 2022). "CCR7/CCL21 promoted survival and metastasis of the CD133+ pancreatic cancer cells via modulation of the ERK/NF-κB pathway." (PMID 35203305, 2022). "CCR7 enhances the migration, invasion, EMT, tumorigenesis, and lymphatic spread in various types of pancreatic cancer cells through the regulation of ERK, PI3K/AKT, and NFκB." (PMID 34948416, 2021). "Our results suggest that Fx suppresses the CCL21/CCR7 axis downstream of Rho signaling, BTLA, TME, EMT, and adhesion in pancreatic tumors in mice." (PMID 34948416, 2021). "There is little information on the CCL21/CCR7 axis, BTLA, TME, EMT, and adhesion signals on the effect of natural compounds on pancreatic cancer." (PMID 34948416, 2021). "The role of CCL21/CCR7 in mediating metastasis and survival of CD133+ pancreatic cancer stem-like cells was detected by Transwell assays and flow cytometry, respectively." (PMID 27505247, 2016). "CCL21/CCR7 promoted metastasis and survival of CD133+ pancreatic cancer stem-like cells and regulated CD133+ pancreatic cancer stem-like cells metastasis by modulating EMT and Erk/NF-κB pathway." (PMID 27505247, 2016). "This study investigated the role of CCL21/CCR7 in promoting EMT and metastasis of cluster of differentiation 133+ (CD133+) pancreatic cancer stem-like cells." (PMID 27505247, 2016). "We therefore evaluated the effect of CCL21/CCR7 on Erk and NF-κB activation in CD133+ pancreatic cancer stem-like cells." (PMID 27505247, 2016). "CCR7 expression was significantly increased in CD133+ pancreatic cancer stem-like cells, resected pancreatic cancer tissues, and metastatic lymph nodes, compared with CD133− cancer cells, adjacent normal tissues and normal lymph nodes, respectively." (PMID 27505247, 2016). "Similar variation patterns were also observed for CCR7 and CCL21 in pancreatic cancer, for CCL21 in squamous cell carcinoma or for CCR7 and VEGF-C in pancreatic ductal adenocarcinoma." (PMID 25744065, 2015). "And the expression of CCR7 and its ligands CCL19/CCL21 in human pancreatic cancer tissue had an obvious correlation with the high rate of lymphatic metastasis." (PMID 24587996, 2014). "Accumulating evidence suggests that over-expression of CCR7 is correlated with lymphatic invasion; CCL21/CCR7 regulated migration and metastasis in a variety of lung, esophageal, and pancreatic cancer cells, possibly allowing them to access the lymphatic system and spread to regional lymph nodes." (PMID 27505247, 2016).
pancreatic cancer (continued). "Additionally, CCR7 induces EMT in the cells of breast, gastric, and pancreatic cancers." (PMID 36980764, 2023). "This apparent contradiction between receptor and ligand expression related to vessel density localized to the pancreatic cancer, such that CCL21 expression was linked to microvessel density but not microlymphatic vessel density, whereas for CCR7 expression, effects were reversed." (PMID 35203305, 2022). "However, the functional inhibition of CCR7 and BTLA may be a key trigger for pancreatic cancer prevention." (PMID 34948416, 2021). "It has also indicated that human pancreatic cancer cells with a high metastatic potential have been shown to upregulate the expression of CXCR4, but not CCR7, resulting in lung and liver metastasis in vivo, and a CXCR4 inhibitor suppressed the metastasis." (PMID 33406809, 2021).